EGFR (epidermal growth factor receptor)
Diseases named in the same sentence as EGFR in open-access papers (continued):
Sharing a sentence is not in itself a finding about the gene and the disease.
non-small cell lung carcinoma (continued). "EGFR signaling mediated autophagy and anti-cancer drug resistance in non-small cell lung cancer cells." (PMID 35682560, 2022). "Epidermal growth factor receptor (EGFR) inhibitors are widely used to treat various types of cancers such as non-small cell lung cancer, head and neck cancer, breast cancer, pancreatic cancer." (PMID 35223483, 2022). "Curcumin potentiates the anticancer activity of gefitinib both in vitro and in vivo through the inhibition of EGFR phosphorylation and induces EGFR ubiquitination in non-small cell lung cancer." (PMID 35745583, 2022). "The addition of gefitinib, an EGFR-TKI used in clinical practice for diseases such as non-small cell lung cancer, significantly decreased the expression of CLDND1, which was increased by EGF." (PMID 35892692, 2022). "Gefitinib is a first-generation EGFR tyrosine kinase inhibitor (TKIs) and its treatment was found to enhance the autophagic process in non-small cell lung cancer." (PMID 35831301, 2022). "Here we present a case of a 68-year-old Asian male with advanced EGFR exon 19 deletion non-small cell lung cancer." (PMID 35651371, 2022). "Third-generation EGFR tyrosine kinase inhibitors (EGFR-TKIs), including osimertinib, an irreversible EGFR-TKI, are important treatments for non-small cell lung cancer with EGFR-TKI sensitizing or EGFR T790M resistance mutations." (PMID 36575215, 2022). "We retrospectively analyzed 1074 patients of non-small cell lung cancer with complete reports of EGFR gene testing." (PMID 35186727, 2022). "Hydroxygenkwanin showed antitumor activity on Non-Small Cell Lung Cancer cells by promoting the degradation of EGFR." (PMID 35704651, 2022). "EGFR-driven non-small-cell lung cancer (NSCLC) patients are currently treated with TKIs targeting EGFR, such as erlotinib or osimertinib." (PMID 36010935, 2022). "In non-small cell lung cancer, oncogenic alterations in the epidermal growth factor receptor (EGFR) increase cellular sensitivity to ferroptosis, due to mitogen-activated protein kinase (MAPK) signaling-mediated NADPH oxidase 4 (NOX4) activation." (PMID 36282248, 2022). "The importance of cell plasticity as a mechanism of treatment tolerance was highlighted in clinical cases of non-small cell lung cancer (NSCLC) treated with epidermal growth factor receptor (EGFR) TKIs, transformed into small-cell lung cancer (SCLC)." (PMID 36034865, 2022). "A similar research has also shown that adding another EGFR monoclonal antibody cetuximab indicated increased survival in advanced non-small-cell lung cancer patients compared with chemotherapy alone." (PMID 35978803, 2022). "Osimertinib—the third-generation epidermal growth factor receptor (EGFR)-tyrosine kinase inhibitor (TKI)—has been widely used as a first-line treatment for patients with metastatic EGFR-mutant non-small cell lung cancer (NSCLC)." (PMID 35698083, 2022). "With respect to EGFR inhibitor-induced differential toxicity, a recent study of non-small cell lung cancer patients treated with erlotinib showed that only the large intestine exhibited signs of erlotinib-induced toxicity." (PMID 35087225, 2022). "Few treatment options are available for brain metastases (BMs) in EGFR-mutant non-small cell lung cancer (NSCLC) that progress with prior EGFR tyrosine kinase inhibitor (EGFR-TKI) therapy." (PMID 36238280, 2022). "Herein, we present a case of a female patient with a darker skin tone with metastatic non-small cell lung carcinoma (NSCLC) with EGFR-TKI-related skin toxicity and her clinical course." (PMID 35448179, 2022). "Different from EGFR and ALK gene mutations, BRAF V600 mutation is relatively rare in non-small cell lung cancer, about 2–3% of which are adenocarcinoma." (PMID 36380085, 2022). "Olmutinib is a third-generation chemotherapeutic drug and an EGFR tyrosine kinase inhibitor (TKI) used to treat non-small cell lung cancer." (PMID 35743930, 2022).
non-small cell lung carcinoma (continued). "Osimertinib is considered the standard-of-care for previously-untreated EGFR mutant advanced non-small cell lung cancer (NSCLC)." (PMID 35847912, 2022). "We conducted a meta-analysis to explore the impact of GASs on the effectiveness and safety of EGFR-TKIs in non-small cell lung cancer (NSCLC) patients." (PMID 35795555, 2022). "Osimertinib, developed to treat drug-resistant non-small cell lung cancer, can inhibit epidermal growth factor receptor (EGFR) tyrosine kinase by MAR with its Cys797 residues on the site reactive to adenosine triphosphate (ATP)." (PMID 36408214, 2022). "Osimertinib, a 3rd generation epidermal growth factor receptor tyrosine kinase inhibitor (EGFR-TKI), is the first-line standard-of-care for EGFR-mutant non-small cell lung cancer (NSCLC) patients, while acquired drug resistance will inevitably occur." (PMID 35197546, 2022). "In our experiments, we expressed Vim-c3GFP in two Non-Small Cell Lung Cancer (NSCLC) cell lines, namely H1975 and A549, which represent classical epithelial cell models for EGFR-mutated and K-Ras-mutated NSCLC adenocarcinoma, respectively." (PMID 35269626, 2022). "EGFR-inhibiting agents such as EGFR-blocking antibodies or EGFR tyrosine kinase inhibitors have been approved to treat various cancers, including colorectal and non-small cell lung cancers." (PMID 35211652, 2022). "IL8 was found to stimulate cell proliferation in non-small cell lung cancer through EGFR transactivation." (PMID 35551547, 2022). "Novel electrochemical sensor-based technologies like an electric field-induced release and measurement (EFIRM) developed by the Wong lab have been shown to detect EGFR mutations (tyrosine kinase domain) from bodily fluids like saliva in patients with non-small cell lung carcinoma (NSCLC)." (PMID 35303879, 2022). "The epidermal growth factor receptor tyrosine kinase inhibitors (EGFR-TKIs) have become an effective treatment for patients with non-small-cell lung cancer (NSCLC)." (PMID 35685507, 2022). "Gefitinib is an EGFR tyrosine kinase inhibitor that can hinder tumor cell proliferation and angiogenesis and has been commercially applied in treating non-small-cell lung cancer." (PMID 35069736, 2022). "KEAP1/NFE2L2/CUL3 represented a mechanism of resistance to tyrosine kinase inhibitor in patients with EGFR-mutant non-small cell lung cancer." (PMID 35371318, 2022). "Especially, significant progresses were achieved in the treatment of non-small-cell lung cancers using EGFR-targeting therapeutics." (PMID 35517789, 2022). "In the past few decades, several gene mutations, including the anaplastic lymphoma kinase, epidermal growth factor receptor, ROS proto-oncogene 1 and rat sarcoma viral oncogene homolog (RAS), have been discovered in non-small cell lung cancer (NSCLC)." (PMID 35517800, 2022). "Gefitinib is the first generation of EGFR-TKIs that was one of the first TKI drugs approved by the FDA for treatment of locally advanced or metastatic non-small cell lung cancer patients." (PMID 35163707, 2022). "Timely identification of epidermal growth factor receptor (EGFR) mutation and anaplastic lymphoma kinase (ALK) rearrangement status in patients with non-small cell lung cancer (NSCLC) is essential for tyrosine kinase inhibitors (TKIs) administration." (PMID 35624472, 2022). "This study aims to explore correlation between gastrointestinal microbiota profile and clinical outcomes in Thai advanced non-small cell lung cancer (NSCLC) according to epidermal growth factor receptor (EGFR) status." (PMID 36076157, 2022). "Among the current targeted therapies, non-small-cell lung cancer targets include EGFR (epidermal growth factor receptor), EML4-ALK fusion gene, ROS1 fusion gene, RAS mutation, and C-MET amplification." (PMID 37492685, 2022). "The five EGFR-TKIs were approved to treat EGFR mutation-positive non-small cell lung cancer (NSCLC) and have a common target gene, EGFR." (PMID 35584089, 2022).
non-small cell lung carcinoma (continued). "Inspired by the critical roles of EGFR reported in reactive oxygen species (ROS)-triggered autophagy in non-small cell lung cancer cells, we focused on the possible involvement of EGFR in CAP-induced autophagy and acetylation alteration." (PMID 35860596, 2022). "The ADAURA trial has been significant for the perception of EGFR tyrosine kinase inhibitors (TKIs) as a tool for early stage non-small-cell lung cancer (NSCLC)." (PMID 35565386, 2022). "In particular, epidermal growth factor receptor (EGFR) activation is common in non-small cell lung cancer, whereas the KIT receptor is the main player in small cell lung cancer." (PMID 35054524, 2022). "Rechallenge of epidermal growth factor receptor-tyrosine kinase inhibitors (EGFR-TKIs) after PD-1 blockade failure was an effective therapy for non-small cell lung cancer (NSCLC) patients with resistance to EGFR-TKIs." (PMID 36457498, 2022). "Increased EGFR activity is characteristic of a number of tumors such as glioblastoma, non-small cell lung cancer (NSCL), head and neck squamous cell carcinoma (HNSCC), and breast, colon, ovarian, prostate, or pancreatic cancer." (PMID 36499115, 2022). "A new era of non-small cell lung cancer (NSCLC) commenced with the appearance of epidermal growth factor receptor (EGFR) tyrosine kinase inhibitors (TKIs)." (PMID 35387120, 2022). "Osimertinib is a third-generation epidermal growth factor receptor (EGFR)-tyrosine kinase inhibitor (TKI) for the treatment of patients with EGFR T790M advanced non-small-cell lung cancer (NSCLC)." (PMID 36034820, 2022). "Formononetin inhibits tumor growth by suppression of EGFR-Akt-Mcl-1 axis in non-small cell lung cancer." (PMID 35372052, 2022). "In this study, we identified LPIN1 as a key factor that regulates gefitinib resistance in epidermal growth factor receptor (EGFR)-mutant non-small cell lung cancer (NSCLC) cells." (PMID 35565351, 2022). "Whole-genome CRISPR screening revealed that mesenchymal EGFR mutant non-small cell lung cancers highly express FGFR1, which promotes DTPs." (PMID 36313710, 2022). "The impact of strong Programmed Death-ligand 1 (PD-L1) expression on the clinical outcomes of osimertinib in treatment naïve advanced Epidermal Growth Factor Receptor (EGFR)-mutant Non-small Cell Lung Cancer (NSCLC) patients remains uncertain." (PMID 35697720, 2022). "ASK120067 showed considerable clinical benefits and safety in patients with EGFR T790M mutant non-small cell lung cancer (NSCLC) in clinical trial (NCT04143607)." (PMID 36588692, 2022). "In a very interesting study of non-small-cell lung cancer cells, the CRISPR/Cas9 system was designed to selectively target EGFR with a single-nucleotide missense mutation (CTG > CGG)." (PMID 35715750, 2022). "Recently, the role of epidermal growth factor receptor (EGFR) translocation to mitochondria was explored in the context of metastatic dissemination of non-small cell lung cancer." (PMID 35356277, 2022). "Ectopic expression of a mitochondrial targeted EGFR (mitEGFR) dramatically increased migration, invasion, and in vivo lung metastasis of non-small cell lung cancer cells injected intravenously." (PMID 35356277, 2022). "For cases diagnosed as non-small cell lung carcinoma (NSCLC) via histology or cytology, targeted testing for epidermal growth factor receptor (EGFR) mutations was performed using tissue biopsy samples (tissue EGFR testing), where available." (PMID 35223889, 2022). "For instance, MET amplification has been proven to be the mechanism of primary resistance to epidermal growth factor receptor (EGFR) tyrosine kinase inhibitor (TKI) therapy in EGFR-mutant non-small cell lung cancer (NSCLC) patients." (PMID 36145516, 2022). "Due to this, CQ was also shown to effectively overcome the innate resistance of wild-type EGFR non-small-cell lung cancer cells to the EGFR inhibitor erlotinib." (PMID 36139404, 2022).
non-small cell lung carcinoma (continued). "In patients with non-small cell lung cancer, EGFR is responsible for approximately 10-20% of all and is the most predominant driver mutations target for targeted therapy." (PMID 35186727, 2022). "Inevitably developed resistance of the third-generation ﻿epidermal growth factor receptor (EGFR) tyrosine kinase inhibitor (TKI) limited its clinical benefit on non-small cell lung cancer (NSCLC)." (PMID 35501907, 2022). "The opposite, positive example is an alteration in exon 19 of the EGFR gene, in particular, for non-small cell lung cancer." (PMID 37181287, 2022). "Mcl-1 upregulation was found to be the main reason for acquired resistance to the third-generation EGFR inhibitor AZD9291 in EGFR-mutant non-small cell lung cancer cell lines." (PMID 36045907, 2022). "EGFR inhibitors as a therapeutic approach for the treatment of EGFR-mutant non-small-cell lung cancer have shown positive results; however, there is a problem of drug resistance." (PMID 35715750, 2022). "Gefitinib, an epidermal growth factor receptor (EGFR) tyrosine kinase inhibitor, has been used in first-line treatment of EGFR-mutant non-small cell lung cancer and can significantly improve progression-free survival in patients." (PMID 35563845, 2022). "Then the combination of heteronemin and tetrac (or NDAT) downregulates EGFR/STAT3 expressions and cell motility in KRAS mutated A549 non-small cell lung cancer (NSCLC) cells." (PMID 35705962, 2022). "Acquired and primary resistance to epidermal growth factor receptor tyrosine kinase inhibitor (EGFR-TKI) is still the bottleneck of clinical treatment of advanced non-small cell lung cancer (NSCLC)." (PMID 36419390, 2022). "A total of 1074 eligible non-small cell lung cancer cases were enrolled in this study, including 527 wild-type EGFR cases and 547 EGFR mutant cases; there were 443 males and 631 females." (PMID 35186727, 2022). "Epidermal growth factor receptor (EGFR)-tyrosine kinase inhibitors (TKIs) have been used, since their invention, as the first-line treatment of non-small-cell lung cancer (NSCLC) patients harboring EGFR mutations." (PMID 35888627, 2022). "These advancements of the tyrosine kinase inhibitors (TKIs), such as gefitinib and erlotinib, which target the epidermal growth factor receptor (EGFR), have led us to personalize the treatment of EGFR-mutant (EGFRm) advanced non-small cell lung cancer (NSCLC)." (PMID 35200593, 2022). "In this study, we show that gefitinib, an inhibitor of epidermal growth factor receptor (EGFR) that is widely used for clinical therapy of non-small-cell lung cancer (NSCLC), strikingly enhances PINK1/Parkin-mediated mitophagy." (PMID 38933121, 2022). "Compared with EGFR-TKIs, immune checkpoint inhibitors (ICIs) have shown promising antitumor effects in non-small cell lung cancer (NSCLC) and are considered to have long-term responses that can potentially lead to cure." (PMID 35990690, 2022). "The use of combination epidermal growth factor tyrosine kinase inhibitor (EGFR-TKI) and immune checkpoint inhibitor (ICI) in EGFR-mutant, advanced non-small cell lung cancer (NSCLC) has raised concerns over the risk of overlapping toxicities." (PMID 35565285, 2022). "EGFR-mutant non-small cell lung cancer (NSCLC) is prone to leptomeningeal metastasis (LM) after Tyrosine kinase inhibitors (TKIs) treatment." (PMID 35287683, 2022). "Epidermal growth factor receptor (EGFR)-tyrosine kinase inhibitor (TKI) monotherapy is the standard of care in treating advanced non-small cell lung cancer (NSCLC)." (PMID 36215289, 2022). "CK1 has been identified to induce acquired resistance to the EGFR inhibitor erlotinib in several EGFR-mutant non-small cell lung cancer (NSCLC) cell lines." (PMID 35360705, 2022).
non-small cell lung carcinoma (continued). "In non-small-cell-lung cancer, MET amplification is thought to be responsible for resistance to targeted drugs in EGFR-mutation-positive patients, which results in malignant biological behavior of tumors, such as invasion, metastasis, escape from apoptosis." (PMID 35401204, 2022). "The A549 cell line, a KRAS mutant and an EGFR wild type epithelial carcinoma obtained from a 58-year-old male patient, is one of the most commonly used cell lines to model non-small cell lung cancer (NSCLC)." (PMID 36077349, 2022). "The epidermal growth factor receptor (EGFR) tyrosine kinase inhibitor osimertinib was recently approved for resected EGFR-mutant stages IB-IIIA non-small cell lung cancer due to improved disease-free survival (DFS) in this population compared with placebo." (PMID 35285487, 2022). "Erlotinib, an orally administered EGFR inhibitor, is currently approved for the treatment of non-small cell lung cancer (NSCLC) and pancreatic cancer, but application in HNSCC was not pursued due to the poor efficacy reported by single-arm clinical trials." (PMID 36110959, 2022). "As a consequence, EGFR-TKI therapy plays a pivotal role in the targeted therapy of patients with non-small cell lung cancer." (PMID 35186727, 2022). "Osimertinib is a third-generation irreversible epidermal growth factor receptor (EGFR) tyrosine kinase inhibitor currently used as first-line systemic therapy for advanced EGFR mutant non-small cell lung cancer." (PMID 35651371, 2022). "The EGFR tyrosine kinase inhibitor afatinib is already used for the therapy of non-small cell lung cancer." (PMID 34064589, 2021). "Resistance to epidermal growth factor receptor tyrosine kinase inhibitors (EGFR-TKIs) is inevitable in EGFR-mutant non-small-cell lung cancer (NSCLC) patients." (PMID 34722761, 2021). "(iii) The clinical trials in non-small cell lung cancer have utilised HGF or c-Met inhibition exclusively to inhibit this pathway (generally in combination with an epidermal growth factor receptor inhibitor)." (PMID 34199452, 2021). "Gefitinib, an epidermal growth factor receptor inhibitor and licensed under the trade name Iressa, has been used in the clinic since 2009 to treat patients with non-small cell lung cancer." (PMID 34722481, 2021). "Epidermal growth factor receptor (EGFR) tyrosine kinase inhibitors (EGFR-TKIs) are the standard of care for non-small cell lung cancer (NSCLC) patients with EGFR exon 19 deletion and L858R mutations." (PMID 34760695, 2021). "This study aimed to systematically investigate the efficacy and safety of the combination of KLT and epidermal growth factor receptor-tyrosine kinase inhibitor (EGFR-TKI) for the treatment of stage III/IV non-small cell lung cancer." (PMID 34588988, 2021). "EGFR tyrosine kinase inhibitor (TKI) resistance in non-small cell lung cancer (NSCLC) patients is inevitable." (PMID 34267282, 2021). "A microarray analysis of non-coding and coding RNAs was performed using parental and resistant EGFR-mutant non-small cell lung cancer (NSCLC) cells and evaluated by bioinformatics analysis through medical-industrial collaboration." (PMID 33924522, 2021). "Rationale: Immune checkpoint inhibitors (ICIs) against the PD-1/PD-L1 pathway showed limited success in non-small cell lung cancer (NSCLC) patients, especially in those with activating epidermal growth factor receptor (EGFR) mutations." (PMID 33537094, 2021). "In afatinib-resistant non-small cell lung cancer cells, overexpression of FGFR1 and FGF2 played a role in overcoming cell survival by compensating the loss of the estrogen growth factor receptor (EGFR)-driven signalling pathway." (PMID 34830836, 2021). "Approved tyrosine kinase inhibitors such as gefitinib, erlotinib and lapatinib (V–VII) for the treatment of non-small cell lung cancer have led to tremendous development of novel EGFR inhibitors in the last decade." (PMID 34832895, 2021).